RN7SL850P (RNA, 7SL, cytoplasmic 850, pseudogene)
Gene: Miscellaneous RNA gene on chromosome 16 (4,633,591 to 4,633,881, reverse strand). Ensembl gene ENSG00000263955.
Homologues: Orthologues: macaque Metazoa_SRP (63% identical). Paralogues in human: Metazoa_SRP (78% identical), Metazoa_SRP (77% identical), RN7SL279P (74% identical), RN7SL32P (74% identical), Metazoa_SRP (71% identical), RN7SL377P (71% identical), RN7SL202P (70% identical), RN7SL356P (69% identical), RN7SL716P (69% identical), Metazoa_SRP (68% identical), RN7SL48P (68% identical), RN7SL155P (67% identical), and 708 more.